RHOA (ras homolog family member A)
Diseases named in the same sentence as RHOA in open-access papers (continued):
Sharing a sentence is not in itself a finding about the gene and the disease.
colorectal cancer (continued). "In colorectal cancer, expression of RhoA is elevated and further results in induction of Tyr705 phosphorylation of STAT3." (PMID 37752569, 2023). "It has been confirmed that the activation of RhoA and Rac1 enhanced the migration of colorectal cancer." (PMID 36969843, 2023). "Wang confirmed that lncRNA LOC441461 promotes tumor growth and mobility in colorectal cancer cells through the RhoA/ROCK signaling pathway." (PMID 35237659, 2022). "It has been reported that Rictor/mTOR is involved in regulating EMT, motility, and metastasis of colorectal cancer via RhoA and Rac1 signaling pathways." (PMID 35982899, 2022). "Recently, MYO1B was reported to aggravate colorectal cancer metastasis via enhancing rearrangement of F-actin and focal adhesion assembly mainly through targeting RhoA." (PMID 35478939, 2022). "Consistently, a recent study reported that YTHDF1 regulates CRC tumorigenesis and metastasis by promoting ARHGEF2 translation and RhoA signaling in colorectal cancer." (PMID 36347025, 2022). "We also provide mechanistic insight into its translational activation ability on Cdc42 and RhoA, thus promoting pseudopodia formation and cytoskeleton reorganization of colorectal cancer cells." (PMID 35300416, 2022). "When inhibiting mTORC1 and mTORC2, found a significantly reduced migration of colorectal cancer cells by regulation of the GTPases RhoA and Rac1." (PMID 35096817, 2021). "Previous research has shown that the overexpression of Tpm2 suppresses cell proliferation and migration by regulating RhoA signaling in colorectal cancer." (PMID 33628783, 2021). "It has also been shown that the level of RhoA expression correlates with the histopathological degree of cancer, and RhoC expression correlates with the extent of local invasion in colorectal carcinoma patients." (PMID 33406809, 2021). "The effect of the circ-133/GEF-H1/RhoA axis on the metastatic potential of colorectal cancer was then further validated in vivo." (PMID 32724467, 2020). "Our results highlight the important role of CXCR4 in promoting inflammation-driven colorectal cancer progression through activation of RhoA/ROCK signaling by lncRNA XIST mediated sponging of miR-133a." (PMID 30678736, 2019). "RhoA plays a role in regulating downstream in the integrin signaling pathway, and knockdown of LRRFIP1/GCF2 reduced activation of RhoA in the colorectal cancer cells plated on fibronectin-coated dishes." (PMID 30709060, 2019). "Colorectal cancer patients with positive RhoA protein expression had higher vascular invasion rates, higher clinical stages, and lower 5-year survival rates." (PMID 31339860, 2019). "Colorectal cancer cells were transfected with miR-133a-3p mimics or inhibitors, RhoA expression was examined by RT-QPCR and Western blot." (PMID 30678736, 2019). "Inhibitions of LRRFIP1/GCF2 by the transfection of short inhibitory RNA (siRNA) into a cervical carcinoma and colorectal cancer cell lines have been shown to reduce RhoA activation, migration, and cytoskeletal remodeling of the transfected cell lines." (PMID 30709060, 2019). "Among them, RhoA and RhoC genes are found to be overexpressed in colorectal cancer and are considered to be potential targets for the management of colorectal cancer." (PMID 29861465, 2018). "Consistently, either inhibiting mTORC1 or mTORC2 is sufficient to induce MET and enhances sensitivity to oxaliplatin-induced apoptosis via RhoA and Rac1 signaling pathways in colorectal cancer cells." (PMID 29609629, 2018). "Elevated mTOR activity regulates EMT, motility, and metastasis of colorectal cancer via RhoA and Rac1 signaling pathways." (PMID 28831205, 2017). "It has been shown that mTORC1 and mTORC2 regulate motility and metastasis of colorectal cancer cells via modulating Ras homolog gene family, member A (RhoA) and Rac1 signaling." (PMID 28701918, 2017). "This fits well with work showing that inactivation of RhoA promotes tumor formation in colorectal cancer models." (PMID 27104658, 2016).
colorectal cancer (continued). "The major finding of this study is that TAp63/miR-133b mediates colorectal cancer suppression through inhibiting RhoA expression and pathways downstream of RhoA." (PMID 27894087, 2016). "Our results suggest that, in addition to survival, proliferation, migration, adhesion, cell cycle and gene transcription, RhoA is also involved in chemoresistance by regulating the expression of membrane transporter and apoptosis protein in colorectal cancer." (PMID 27888624, 2016). "In a mouse model of colorectal cancer, metastatic sites were found to have lower RhoA signaling than the primary tumors, and this held for samples from human tumors as well." (PMID 27104658, 2016). "In this study, we first compared the invasiveness of a collection of colorectal cancer cell lines with their RhoA, Rac1 and Cdc42 activities." (PMID 23144867, 2012). "ROCK-1, which is activated by activated RhoA, promotes cell invasion and motility in prostate cancer and colorectal carcinoma cells." (PMID 21119662, 2011). "RhoA and RhoC have been proved to be over-expressed in many solid cancers, including colorectal cancer." (PMID 20828398, 2010). "The present study was to evaluate the effect of silencing of RhoA and RhoC expression by RNAi on growth of human colorectal carcinoma (CRC) in tumor-bearing nude mice in vivo." (PMID 20828398, 2010). "In this study, for the first time we constructed recombinant adenovirus to investigate the inhibitory effects of RhoA and RhoC shRNAs in tandem expression on the cell proliferation and invasion of colorectal cancer HCT116 cells." (PMID 19374769, 2009). "In this study, for the first time we constructed adenovirus vector carrying RhoA and RhoC shRNAs in tandem expression and investigated the inhibitory effects of recombinant adenovirus on the cell proliferation and invasion of colorectal cancer HCT116 cells." (PMID 19374769, 2009). "IRX5 promoted the metastasis of colorectal cancer by regulating the RHOA pathway." (PMID 40672387, 2025). "This suggests that higher levels of RhoA expression may be indicative of more advanced stages of colorectal cancer." (PMID 39887960, 2025). "In addition, YTHDF1 escalates the translation of ARHGEF2, activating RhoA signaling, thereby driving tumorigenesis and metastasis in colorectal cancer." (PMID 40251202, 2025). "ARHGAP5 drives colorectal cancer metastasis through the negative regulation of RhoA activity." (PMID 38783033, 2024). "In addition, it has been reported that AAMP is abnormally up-regulated in metastatic CRC and boosts the occurrence of colorectal cancer by inhibiting SMURF2-mediated RhoA liquefaction and degradation." (PMID 37501187, 2023). "Similarly, YTHDF1 promotes ARHGEF2 translation in an m6A-dependent manner and promotes progression of colorectal cancer through RhoA signaling." (PMID 37259333, 2023). "LRRFIP1 promoted colorectal cancer metastasis and liver invasion through RhoA activation." (PMID 35338570, 2022). "Additionally, studies have shown that IRX5 can negatively regulate RhoA/ROCK1/LIMK1 signaling pathway to promote the metastasis of colorectal cancer cells." (PMID 34486491, 2021). "Likewise, Rho GTPases such as RhoA, RhoC and Rac1 were found to be upregulated in colorectal carcinoma." (PMID 34151400, 2021). "Moreover, CXCR4 was remarkably expressed in the cytoplasm and membrane of colon cancer cells and RhoA was predominantly expressed in the cytoplasm of colorectal cancer tissues." (PMID 30678736, 2019).
colorectal cancer (continued). "A study in colorectal cancer indicated a strong correlation of both RhoA and RhoC in metastasis and invasion, whereas other studies in breast and colon cancer have suggested that RhoA often inhibits cell invasion, while RhoC, on the other hand, enhances cell invasion." (PMID 31340863, 2019). "However, inactivation of RhoA can contribute to colorectal cancer progression and metastasis through activation of Wnt/β-catenin signaling." (PMID 31004081, 2019). "However, there is some contradictory evidence showing that RhoA inactivation promoted the migration and metastasis of triple-negative breast cancer and increased tumor growth and metastasis in colorectal cancer, liver cancers, and nasopharyngeal carcinoma." (PMID 31339860, 2019). "Consistent with our findings, a previous study found that the downstream serine/threonine kinase mTOR, which is known to be an important upstream regulator of SGK1 and plays a crucial role in promoting EMT via RhoA and Rac1 signaling in colorectal cancer (CRC)." (PMID 29609629, 2018). "Lin and Qin reported RhoA as a direct target of miR-133b in cervical and colorectal cancer." (PMID 27894087, 2016). "Our study has provided a novel insight into the molecular mechanisms of drug resistance in colorectal cancer, and suggested that targeting RhoA signaling might improve the effectiveness of clinical treatment of colorectal cancer." (PMID 27888624, 2016). "In another study, RhoA activity correlated with lymph node metastasis in human colorectal cancer." (PMID 24646293, 2014). "We then assessed whether invasiveness and the level of active Rho GTPases, which are key components of the invasive machinery, were correlated by comparing the level of GTP-bound Cdc42, Rac1 and RhoA in the different colorectal cancer cell lines." (PMID 23144867, 2012). "RhoA and RhoC are deregulated by over expression in many human tumors, including colorectal cancer." (PMID 19374769, 2009). "We showed that a significant reduction in RhoA and RhoC expression could markedly inhibit the invasion and migration potentials of colorectal cancer cells." (PMID 19374769, 2009). "Increased levels of RhoA expression was observed in Asian patients with colorectal carcinoma." (PMID 19374769, 2009). "Also, the accumulation of IGF2BP2 could activate the RhoA/Rock pathway, which in turn promoted M2 macrophage polarization and accelerated colorectal cancer progression." (PMID 39014364, 2024). "Taken together, these data suggest that in clinical colorectal cancer patients high CXCR4 expression contribute to CRC progression and invasion through recruiting macrophages and upregulation of RhoA by repressing miR-133a-3p." (PMID 30678736, 2019). "Studies have also suggested that miR-185 can downregulate the activity and function of RhoA and Cdc42 by targeting sites in the RhoA and Cdc42 3’UTR, which then can suppress the proliferation and invasiveness of the colorectal cancer cells." (PMID 29596304, 2018). "To determine if RhoA is involved in chemoresistance in colorectal cancer, we first examined the expression of RhoA in CPT-11-resistant colorectal cancer cells (SW620/CPT-11 and LoVo/CPT-11) and parental cells." (PMID 27888624, 2016). "Other mutual exclusivities have been observed between HRAS and RHOA, in head and neck squamous cell carcinoma (HNSC) and between DIRAS2 and KRAS in colorectal cancer." (PMID 26860319, 2016). "However, whether and how RhoA regulates drug resistance in colorectal cancer are poorly understood." (PMID 27888624, 2016). "For example, CCL20, by binding to CCR6, regulates the ability of cells to migrate and invade by activating the RhoA pathway in colorectal cancer, a role not commonly seen in other chemokines." (PMID 38791448, 2024). "Beside this, RHOA was found to be upregulated in chemoresistant-CRC, playing a role in the expression of cell membrane transporter and apoptosis in colon cancer, contributing to chemotherapeutic resistance in colorectal cancer patients." (PMID 33406731, 2021).
colorectal cancer (continued). "We conclude that, in the tested colorectal cancer cell lines, the level of active Cdc42 and Rac1, but not of RhoA, is inversely correlated with the invasiveness of such cells (respective p values: 0.0008, 0.0003 and 0.134)." (PMID 23144867, 2012). "Thus vincristine increased ability of human colorectal cancer HCT116 cells to migrate through the filters in the Transwell assay and stimulate amoeboid-like motility of MKN45 cells by activating RhoA/ROCK/MLC signaling pathway." (PMID 36278174, 2022). "Moreover, miR-185 is a negative regulator of RhoA and CDC42, and could inhibit the proliferation and invasion of human colorectal cancer cells." (PMID 33152231, 2021). "Examples discussed in this review include Cdc42, Rac1, RhoA, RhoC and RhoH activation of oncogenic STAT3, and in some cases STAT5, in a range of cancers including but not limited to: breast, bladder, gastric, cervical, myeloid, pancreatic, hepatocellular, head and neck, and colorectal cancer." (PMID 32915198, 2020). "However, no prominent change in RhoA activation was detected in several breast and colorectal cancer cell lines under Wnt-on conditions." (PMID 27779255, 2016). "We show that the ability to invade of these colorectal cancer cell lines is correlated with a marked decrease in Cdc42 and Rac1 activity and an increase in ROCK, but not RhoA, activity." (PMID 23144867, 2012).
colon carcinoma (83 papers, 2009 to 2026). "5‐HT enters cells via SERT and activates the Ras homolog family member A (RhoA)/Rho‐associated kinases (ROCKs)/Yes‐associated protein (Yap) signaling pathway, thereby promoting the development of colon cancer." (PMID 40937192, 2025). "They include upregulation of RhoA and ROCK1 expression, acquiring activating mutations of ROCK1 in microsatellite-instable colon cancer, as well as frequent inactivating mutations of upstream negative regulators of RhoA, Rho GTPase-activating proteins." (PMID 33670106, 2021). "Decreased RhoA protein expression by RhoA small interfering RNA was associated with the increased sensitivity to doxorubicin in human colon cancer cell line." (PMID 30001383, 2018). "Our findings are in line with that by Carloni V who has shown that RhoA is involved in cell fusion and causes the appearance of cells resistant to both 5-fluorouracil and oxaliplatin in a metastatic model of colon carcinoma." (PMID 27888624, 2016). "CXCR4 is a direct target of miR-126 in human colon cancer cells, miR-126 is reversely associated with RhoA activity in vitro." (PMID 27517626, 2016). "We investigated the effects of AZA197 treatment on RhoA, Rac1 and Cdc42 activities and associated molecular mechanisms in colon cancer cells in vitro." (PMID 24279335, 2013). "Human breast, ovarian, renal, lung and colon tumor specimens have been analyzed for somatic RHOA mutations previously." (PMID 21884569, 2011). "The up-regulated RhoA activity causes dephosphorylation of ezrin/radixin/moesin proteins and destruction of plasma membrane-cortical actin interaction, promoting fusion of human metastatic colon cancer cells and cell acquisition of drug resistance." (PMID 35237598, 2022). "Indeed, CCL17/CCR4-dependent colon cancer cell migration is associated with increased activity of RhoA and can be inhibited by targeting Rho-kinase function." (PMID 28146427, 2017). "Increased RhoA expression has been described in various human tumors including colon cancer associated with malignant progression, although Rho GTPases also seem to have a tumor suppressive function since loss of Rho function is associated with predisposition to lymphoid cell transformation." (PMID 24279335, 2013). "SAR1A is upregulated in colon cancer and osteosarcoma, where it promotes osteosarcoma cell metastasis through the RhoA/YAP pathway, ER stress, and autophagy." (PMID 39595043, 2024). "Regulation of RhoA by AAMP has been previously shown in colon cancer cells, vascular smooth muscle cells, and ECs." (PMID 39404373, 2024). "This outcome confirmed RhoA/ROCK’s critical effect on its signalling axis in YAP-mediated regulation of 5-HT in colon cancer cells." (PMID 37046308, 2023). "Together, our findings suggested that serotonin enters cells via SERT to activate RhoA/ROCK/YAP signalling to promote colon cancer carcinogenesis." (PMID 37046308, 2023). "Meanwhile, 100 μM citalopram reversed 5-HT-induced active RhoA expression, suggesting that RhoA was responsible for 5-HT-induced YAP expression in colon cancer cells." (PMID 37046308, 2023). "Xiao’ study indicated that lovastatin suppressed the canonical Wnt/β-catenin and alternative Wnt-YAP/TAZ pathways via inhibiting RhoA activity in colon cancer cells." (PMID 37974278, 2023). "In summary, we reported that SERT was responsible for transporting serotonin into colon cancer cells which TG2-mediated serotonylation to activate RhoA." (PMID 37046308, 2023). "In UC-associated colon cancer, CXCR4 promotes the progression of the disease by recruiting immune cells and enhancing cytoskeletal remodeling through the lncRNA XIST/miR-133a-3p/RhoA signaling." (PMID 36061211, 2022). "DLC1 is a GAP for RhoA, which is often deleted in hepatocellular carcinoma and inactive in various types of human cancers including colon cancer." (PMID 34958986, 2022).